GRP (gastrin releasing peptide)
Diseases named in the same sentence as GRP in open-access papers (continued):
Sharing a sentence is not in itself a finding about the gene and the disease.
tumor (continued). "Some peptidergic genes such as CALCA and GRP that are expressed in almost all normal PNECs were expressed in few if any tumor cells, whereas NPW, NMB, and CARTPT that are expressed in only rare PNECs were expressed in most (NPW) or many (NMB, CARTPT) of the tumor cells." (PMID 36469459, 2022). "Gastrin-releasing peptide (GRP) and its receptor (GRPR) have been reported to be aberrantly expressed in the colon after malignant transformation and have been associated with delayed tumor recurrence and improved survival." (PMID 35479956, 2022). "The GRP score, when combined with data on tumour immune cells, could be used in predicting chemosensitivity of PDAC." (PMID 33942483, 2021). "In addition to OS, tumour size was positively correlated with the GRP score in PDAC patients in the TCGA cohort (chi‐square test, P < .05)." (PMID 33942483, 2021). "Additionally, it was observed that NmB is 50–100% more effective in pro-proliferative activity on tumor cells compared to GRP." (PMID 32429087, 2020). "Furthermore, there was a correlation between pro-GRP levels with the best percentage tumor change and M30 levels also displayed a direct correlation with navitoclax doses." (PMID 33381025, 2020). "GRP and NMB secretion by SCLC is known to cause an autocrine growth loop that drives tumour growth." (PMID 31921534, 2019). "Several neuropeptide growth factors, including gastrin releasing peptide (GRP), neuromedin-B, gastrin, cholecystokinin, neurotensin, vasopressin, galanin and bradykinin, have been implicated in self-promoting tumour growth by acting through autocrine growth loops." (PMID 28595067, 2017). "Gold nanoparticles have been used as a micro-CT contrast agent for the targeting of multiple tumor markers, including Her2, the gastrin-releasing peptide (GRP) receptor, the epidermal growth factor receptor (EGFR), the folic acid receptor (FAR), and tumor microcalcifications." (PMID 26581654, 2015). "Finally, we demonstrate that GRP silencing reduced primary tumor growth and inhibited liver metastasis in our in vivo tumor-metastasis model." (PMID 24039782, 2013). "Similarly, the GRP reduced tumor size (approximately 2-fold) significantly more than the control groups when mice received the vaccine after-tumor inoculation." (PMID 21385454, 2011). "In addition, GRP is able to contribute indirectly to tumor angiogenesis by augmenting expression of pro-angiogenic factors such as IL-8 and VEGF." (PMID 21385454, 2011). "This may be useful in tailoring therapy to a specific tumour phenotype in as much as SP-G may be more beneficial in V1A receptor expressing tumours while SP-D may be better for tumours, which express both GRP and V1A receptors." (PMID 15685238, 2005). "The tumour-inhibitory effect of bombesin/GRP antagonists appears to involve complex mechanisms." (PMID 14710236, 2004). "Analysis of differential expression between GC tumor tissues and normal tissues revealed upregulated SERPINE1, IL1F10, IGFBP1, and ITIH2, whereas C6, GCG, GRP, and APOD were downregulated." (PMID 41551463, 2026). "Mechanistic studies revealed that BU peptide inhibits GRP–GRPR-mediated activation of the PI3K/Akt and MAPK/ERK signalling pathways, known to be key regulators of tumour cell survival and proliferation." (PMID 41226822, 2025). "The pro-gastrin-releasing peptide (ProGRP) is a stable precursor of gastrin-releasing peptide (GRP), a neuropeptide involved in tumor growth and differentiation." (PMID 40869471, 2025). "Pro-gastrin-releasing peptide (pro-GRP), the precursor to gastrin-releasing peptide (GRP), is another established tumour marker." (PMID 39888565, 2025). "While Demobesin 1 acted as a potent antagonist, reversing the stimulatory effects of gastrin-releasing peptide (GRP) substrates, Demobesin 4 demonstrated higher internalization in HEK293 and PC3 cell lines, showcasing its potential as a tumor-targeting agent." (PMID 40428099, 2025).
tumor (continued). "Tumor size before chemotherapy, pre-chemotherapy NSE, post-cycle 2 FIB, post-cycle 2 gastrin-releasing peptide precursor, and NSE change values were included in the multivariate logistic regression analysis." (PMID 41018085, 2025). "Serum B-type natriuretic peptide was 160 pg/mL and pro-gastrin-releasing peptide (Pro-GRP) 426 pg/mL; other tumor markers (NSE, CEA, SCC, C21-1, and alpha-fetoprotein [AFP]) were normal." (PMID 40958226, 2025). "Pro-gastrin-releasing peptide precursor (ProGRP) and neuron-specific enolase (NSE) tumour markers are recommended in the literature for early diagnosis." (PMID 40951894, 2025). "Subsequent experiments have demonstrated that pro-GRP can not only be utilized in the early diagnosis of SCLC but also aid in assessing treatment effectiveness and detecting tumor recurrence in a timely manner." (PMID 38279185, 2024). "The five tumor markers, CEA, CA125, CY211, NSE, and GRP, demonstrated validity in screening both healthy individuals and patients with pulmonary carcinoma." (PMID 38549716, 2024). "Approximately two-thirds of SCLC tumors produce gastrin-releasing peptide precursor (pro-GRP), which establishes the theoretical basis for pro-GRP as a specific tumor marker for SCLC." (PMID 38279185, 2024). "In contrast, the concentrations of the tumor markers CEA (P <0.001), NSE (P <0.001), and GRP (P <0.001) were significantly higher in patients with pulmonary cancer than in those with benign lung disease." (PMID 38549716, 2024). "Meantime, the complementary performance of three conventional tumor markers (NSE, SCC, and Pro-GRP) for 4MP was assessed." (PMID 37476198, 2023). "Tumor markers, including carcinoembryonic antigen (CEA), cytokeratin fragment (CYFRA) 21, and pro-gastrin-releasing peptide (Pro-GRP), were within the normal ranges." (PMID 39516940, 2023). "After univariable and multivariable logistic regression analysis of blood tumor markers (CEA, CYFRA21-1, SCC, NSE, and Pro-GRP), only CEA was an independent factor for HRPNs (OR=1.701, 95% CI: 1.072-2.701, P=0.024)." (PMID 37361581, 2023). "Gastrin releasing peptide (GRP) and its receptor (GRPR) are morphogenetic factors, which keep tumor cells at high degree of differentiation and reduce tumor metastasis ability." (PMID 37228820, 2023). "Blood tests show a significant elevation of tumor markers including neuron-specific enolase (NSE) and pro-gastrin-releasing peptide (Pro-GRP) than the normal." (PMID 36532013, 2022). "The expression of serum tumor markers carcinoembryonic antigen (CEA) and pro-gastrin-releasing peptide (proGRP) was elevated in LCNEC." (PMID 36304941, 2022). "Subsequently, we analyzed the correlation between the number of CTCs and serum tumor markers (CEA, NSE, pro-GRP, and CYFRA21-1) in malignant nodule patients." (PMID 33905377, 2021). "In this signature, up-regulated DKK1 and GRP together with down-regulated FAS and CD1B had significant correlation with tumor stage, metastasis and lymphatic invasion." (PMID 33996273, 2021). "Serum tumor marker levels were CEA 5.8 ng/ml; CYFRA 2.1 ng/ml; pro‐GRP 30.7 pg/ml; and NSE 6.8 ng/ml." (PMID 34622569, 2021). "In our study, we performed ROC curve analysis of serum tumor markers (CEA, NSE, pro-GRP, and CYFRA21-1) in the 120 enrolled patients with pulmonary nodules." (PMID 33905377, 2021). "Serum tumor marker levels at diagnosis were CEA 13.7 ng/ml; CYFRA 26.6 ng/ml; pro‐GRP 67.0 pg/ml and NSE 18.4 ng/ml." (PMID 34622569, 2021). "The pro-GRP was known as a surrogate marker of BCL-2 amplification and its changes correlated with changes in tumor volume." (PMID 33381025, 2020). "Doxorubicin has been chemically conjugated to a number of other peptides, including cell penetrating peptides (CPP), tumor homing peptide Lyp-1, RGD peptides, somatostatin, and bombesin/gastrin-releasing peptide (BN/GRP), and broadly studied." (PMID 31091786, 2019).
tumor (continued). "Gold nanoparticles have been used as a micro-CT contrast agent for the targeting of multiple tumor markers in mice, including Her2, the gastrin-releasing peptide (GRP) receptor, the folic acid receptor (FAR), the LDL receptor, and tumor microcalcifications." (PMID 30408128, 2018). "Elevated values of tumor markers were detected in 35.7% (5/14) for CEA, 7.1% (1/14) for SCC, 44.4% (4/9) for NSE and 50% (3/6) for Pro-GRP." (PMID 28288180, 2017). "Our patient had elevated tumor marker levels before chemotherapy: with 4.0 ng/mL of neuron-specific enolase (NSE) and 58.5 pg/mL of pro-gastrin-releasing peptide (proGRP)." (PMID 29052535, 2017). "In case 3, the Pro-GRP and CEA levels were elevated simultaneously, indicating that adenocarcinoma cells were included in the tumor." (PMID 24396447, 2014). "The tumor markers, CEA and Pro-GRP, were elevated with values of 10.5 and 468.1 pg/ml, respectively." (PMID 24396447, 2014). "The levels of the tumor markers, carcinoembryonic antigen (CEA), CYFRA21-1 and pro-gastrin-releasing peptide (Pro-GRP), were within normal limits." (PMID 24396447, 2014). "Bombesin-like peptides, including NMB and gastrin-releasing peptide (GRP), are released by malignant tumor cells and act as autocrine growth factors and mitogens that influence proliferation and cell cycle progression." (PMID 24349381, 2013). "Inhibition of GRP led to increased expression of PTEN, a negative regulator of the PI3K/AKT pathway, which is known to activate tumor proliferation and survival signaling." (PMID 24039782, 2013). "In this case, transitions in tumor markers (SLX and pro-GRP) appeared to occur in parallel with histological transformation." (PMID 24195468, 2013). "Tumor imaging and PRRT have been extended to many other receptors such as Gastrin-releasing peptide/bombesin (GRP) and Cholecystokinin (CCK) in recent years." (PMID 23316341, 2012). "Laboratory findings and results for tumor markers such as CEA (carcinoembryonic antigen), NSE (neuron specific enolase), and ProGRP (pro-gastrin releasing peptide) were all within normal ranges, preoperatively." (PMID 21092193, 2010). "Serum tumor markers were as follows: alpha-fetoprotein (AFP), 8.51 ng/mL; carcinoembryonic antigen (CEA), 5.79 ng/mL; neuron-specific enolase (NSE), 34.40 ng/mL; and pro-gastrin-releasing peptide (ProGRP), 76.50 ng/mL." (PMID 41438978, 2025). "The sensitivity of five tumor markers—CEA, CYFRA21-1, NSE, pro-GRP, and CA125—was found to be <55%." (PMID 38549716, 2024). "We collected clinicopathological data, including tumor pathological grading, staging, serum concentrations of neuron-specific enolase (NSE) and pro-gastrin-releasing peptide, levels of inflammatory factors, and expression of oxygen 6-methylguanine-DNA methyltransferase (MGMT)." (PMID 39061142, 2024). "Tumor markers: gastric protease I, gastric protease II, alpha-fetoprotein (AFP), carbohydrate antigen, cytokeratin 19 fragment, gastrin-releasing peptide precursor, total prostate-specific antigen, free prostate-specific antigen, carcinoembryonic antigen, neuron-specific enolase." (PMID 38115262, 2023). "Unfortunately, traditional tumor markers, such as cytokeratin fragment 21–1 (CYFRA21-1), pro-gastrin-releasing peptide (ProGRP), carcinoembryonic antigen (CEA), and neuron-specific enolase (NSE), are limited in clinical use due to their poor sensitivity and specificity values." (PMID 37699023, 2023). "The CD1A, CD1B, GRP, SERPINE1, and F2RL2 genes were highly expressed in tumor tissue." (PMID 36221049, 2022). "GRP-R-based pharmaceuticals and specific radioactive, cytotoxic, and nonradioactive GRP-analogs have been designed and tested in various animal tumor models with the aim of receptor targeting for tumor diagnosis or anti-cancer therapy." (PMID 36525420, 2022).
tumor (continued). "have reported that GRP/GRPR is responsible for promoting the binding of CD16+ and CD94+ natural killer cells following inducing expression of Hsp72 by signaling via focal adhesion kinase, thus contributing to tumor cell cytolysis." (PMID 36518255, 2022). "Serum tumor marker levels at diagnosis were carcinoembryonic antigen (CEA) 13.5 ng/ml; cytokeratin‐19 fragment (CYFRA) 4.9 ng/ml; progastrin‐releasing peptide (pro‐GRP) 63.5 pg/ml; and neuron‐specific enolase (NSE) 10.5 ng/ml." (PMID 34622569, 2021). "In addition, 19 patients were reported to have changes in tumor biomarkers; 14 patients were found to have an increase in neuron-specific enolase (NSE) and eight patients had an increase in prn-gastrin-releasing peptide (Pro-GRP)." (PMID 34435141, 2021). "Progastrin-releasing peptide (ProGRP), used as a biochemical marker, is the precursor of GRP and is used as a tumor marker instead of nonstable GRP because its half-life is very short." (PMID 31091854, 2019). "Serum tumor marker sensitivity was 28.46% (35 patients) for CEA, 19.51% (24 patients) for CA 125, 3.25% (4 patients) for NSE, 50.41% (62 patients) for CYFRA 21‐1, 26.02% (32 patients) for SCC, and 11.38% (14 patients) for Pro‐GRP." (PMID 31132233, 2019). "Moreover, previous study had confirmed that plasma CYFRA21-1 appeared more sensitive for NSCLC diagnosis than other tumor biomarkers such as carcinoembryonic antigen (CEA) and neuron-specific enolase (NSE) and progastrin-releasing peptide (ProGRP)." (PMID 28422739, 2017). "In immunohistochemistry, a panel of different antibodies, such as carcinoembryonic antigen (CEA), gastrin-releasing peptide (GRP), cytokeratin (CK) 5/6, thyroid transcription factor 1 (TTF-1), p63, and thrombomodulin (CD141), is applied for biomarker detection on tumor cells." (PMID 28325282, 2017). "However, expression of GRP and GRP-R is an important feature of NED/NE tumor, and GRP-R is clinically targetable by using analogue-based approach directed against the receptor (such as targeted radiotherapy)." (PMID 27542219, 2016). "Bombesin peptide-functionalized AuNPs exhibited GRP-enhanced tumor accumulation and decreased liver uptake compared with nonspecific protein-conjugated AuNPs." (PMID 28347100, 2015). "The levels of the tumor markers, CEA, CYFRA21-1 and Pro-GRP, were within normal limits." (PMID 24396447, 2014). "Tumor markers such as SLX and pro-GRP reflected the pathological changes in the tumor." (PMID 24195468, 2013). "Gastrin Releasing Peptide (GRP), a 27-mer amino acid peptide, is an autocrine/paracrine growth factor that belongs to the bombesin peptide family of neuropeptides involved in many steps of tumor progression including angiogenesis." (PMID 21385454, 2011). "Pro-gastrin-releasing peptide (ProGRP) and neuron specific enolase (NSE) have become hotspot of tumor markers for small cell lung cancer (SCLC), and the aim of this study is to evaluate and compare the diagnostic value of serum ProGRP and NSE in SCLC by meta-analysis." (PMID 21159242, 2010). "O + /A + tumors showed solid-spindle features and diffuse GRP and frequent ACTH expression, trabecular patterns characterized ASCL1-negative tumors, while oncocytic histology predominated in OTP-negative tumors, highlighting their role in defining tumor heterogeneity." (PMID 41196447, 2025). "GRP stimulation markedly increased the phosphorylation of Akt at Ser473 and ERK1/2 at Thr202/Tyr204, consistent with the activation of the PI3K/Akt and MAPK/ERK pathways, which are known to promote tumour cell proliferation, survival, and resistance to apoptosis." (PMID 41226822, 2025). "Additionally, the levels of serum neuron specific enolase (NSE) & pro-gastrin-releasing peptide (ProGRP) also had no implication on tumor shrinkage rate and PFS." (PMID 39327433, 2024).
tumor (continued). "We found two deleted regions shared by both tumor types in three out of the four cell lines H23R, A2780R, and OVCAR3R, but not in H460 cells, located on 18q21.2–18q21.31 and 18q21.32, affecting the genes RAB27B, CCDC68, TCF4, TXNL1, WDR7, and BOD1P; and genes ZNF532, SEC11C, GRP, respectively." (PMID 32224864, 2020). "Therefore, inhibiting ARVs expression by blocking GRP/GRP-R signaling may not be sufficient to control AR negative NE tumor growth." (PMID 27542219, 2016). "The complete blood count, C-reactive protein (CRP), procalcitonin, erythrocyte sedimentation rate (ESR), G test, GM test, and tumor markers including CEA, SCC, CA125, pro-GRP and NSE were normal." (PMID 41140660, 2025). "All prognostic scores discussed here do not consider tumor markers that are commonly used in clinical practice, such as neuron-specific enolase (NSE) or pro-gastrin-releasing peptide (ProGRP)." (PMID 35681605, 2022). "Blood chemistry results showed no elevated level of the tumor markers carcinoembryonic antigen (CEA), cytokeratin 19 fragment (CYFRA), neuron-specific enolase (NSE), squamous cell carcinoma related antigen (SCC), and pro-gastrin releasing peptide (pro-GRP)." (PMID 40502213, 2025). "Lack of or significantly lower tumor expression versus control, which might also play a role in LM, was demonstrated for several NP/NP-Rs system components: CRHR2, GRP/GRPR, SM, Sst2, as well as Sst2 and Sst5." (PMID 32429087, 2020). "In a selected panel of tumour cell lines (SCLC, non-SCLC, ovarian, colorectal and pancreatic), the expression of the mitogenic neuropeptide receptors for vasopressin, gastrin-releasing peptide (GRP), bradykinin and gastrin was examined, and their sensitivity to SP-G tested in vitro and in vivo." (PMID 12771999, 2003).